MGMT (O-6-methylguanine-DNA methyltransferase)
Diseases named in the same sentence as MGMT in open-access papers (continued):
Sharing a sentence is not in itself a finding about the gene and the disease.
glioblastoma (continued). "A survival benefit was observed in LGGs contained a methylated MGMT; Similar to glioblastoma, MGMT-non-pM confers a shorter OS (3 years vs. not reached) and PFS (2 years vs. not reached) compared with MGMT-pM in high-risk LGGs." (PMID 34412650, 2021). "Not all glioblastoma patients with MGMT promoter methylation respond to alkylating agents, and even those who respond eventually experience relapse." (PMID 33661424, 2021). "There were equal numbers of glioblastoma cases with MGMT-methylation (n = 26) and without MGMT methylation (n = 26)." (PMID 33661424, 2021). "That is, there is a lack of benefit of temozolomide for MGMT methylated patients with high vascular glioblastomas." (PMID 34771583, 2021). "In this study, we evaluated the benefit on survival of the combination of methylation of O6-methylguanine-DNA methyltransferase (MGMT) promotor gene and moderate vascularity in glioblastoma using a retrospective dataset of 123 patients from a multicenter cohort." (PMID 34771583, 2021). "One well known example is the promoter methylation of MGMT, not its gene expression correlates well to the efficacy of Temozolomide in glioblastoma multiforme." (PMID 34418985, 2021). "MGMT promoter methylation is the most predictive factor associated with longer survival in patients with glioblastoma who receive TMZ, and the gene microarray showed that the expression of MGMT was not changed after indirect coculture with gaMSCs (P > 0.05)." (PMID 34256854, 2021). "Similarly, a prospective cohort study of the German Glioma Network of 233 glioblastoma patients aged ≥ 70 years revealed longer PFS (5.2 vs. 4.7 months) and OS (8.4 vs. 6.4 months) in patients with MGMT promoter-methylated tumours." (PMID 32748120, 2021). "Postoperative treatment with PD1 antibody and radiation therapy in O6-methylguanine DNA methyltransferase (MGMT)-unmethylated newly diagnosed glioblastoma did not improve overall survival compared with radiation therapy and temozolomide (NCT02617589)." (PMID 34063518, 2021). "A significant difference in recurrence interval was observed among glioblastoma patients with methylated and none-methylated MGMT, who received different chemotherapeutic protocols (adjusted P-value = 0.041)." (PMID 33661424, 2021). "Previous studies showed increased double strand DNA damage in MGMT‐negative glioblastoma cell lines treated with RT combined with temozolomide compared to single treatment." (PMID 34477324, 2021). "Overall, the data support metronomic (dose-dense) TMZ administration and suggest that even low doses are effective in glioblastoma therapy, which applies at least to promoter methylated MGMT-lacking tumors." (PMID 34944906, 2021). "Patient 1 was a 33-year old male (sGB_6) diagnosed with astrocytoma, IDH-mutant (WHO grade II) and relapse with a secondary glioblastoma without MGMT methylation." (PMID 32758285, 2020). "Importantly, EGCG inhibits the expression of O6-Methylguanine DNA-Methyltransferase (MGMT) in GBM-derived cells only, which is an essential regulator of the resistance to temozolomide (TMZ) in glioblastomas." (PMID 32075265, 2020).
glioblastoma (continued). "Hence we investigated the most important chemotherapy paradigm for glioblastomas, the alkylating agent TMZ against the background of variable MGMT promoter methylation presumably resulting in epigenetic silencing." (PMID 33318498, 2020). "Consensus on MGMT testing would increase the validity of informed decision making regarding treatment with TMZ and other alkylating agents in the everyday care of patients with glioblastoma." (PMID 32025325, 2020). "According to the current results, mifepristone could possibly contribute to the modulation of tumor relapse in glioblastoma by decreasing the levels of VEGF, MGMT, and P-gp." (PMID 33123485, 2020). "In total, 326 IDH-wildtype glioblastoma were included in our analysis: 177 (54.3%) with and 149 (45.7%) without MGMT promoter methylation." (PMID 32766140, 2020). "Tumors were semi-automatically segmented, and the topographical distribution between glioblastoma with vs. without MGMT promoter methylation was visualized using frequency heatmaps." (PMID 32477929, 2020). "When compared with MGMT unmethylated glioblastoma, MGMT methylated glioblastoma had a significantly higher ratio of non-enhancing vs. contrast-enhancing volume [2.09 (inter quartile range 2.6) and 2.5 (inter quartile range 3.3), p = 0.045, respectively]." (PMID 32477929, 2020). "For example, although MGMT methylation status was not prospectively assayed in the pivotal EORTC/NCIC trial of adjuvant TMZ in adults with glioblastoma, patients with tumors exhibiting unmethylated MGMT promoter regions derived less benefit." (PMID 33216844, 2020). "Surprisingly, methylation of MGMT promoter did not predict response to temozolomide in patients with glioblastoma in Donostia Hospital." (PMID 33116181, 2020). "Final analysis included 436 patients with IDH wildtype glioblastoma (see flowchart); 211 with and 225 without MGMT promoter methylation." (PMID 32477929, 2020). "We initiated this study to re-evaluate the topographical distribution of glioblastoma with vs. without MGMT promoter methylation in light of the updated WHO 2016 classification." (PMID 32477929, 2020). "In the results of the AVAglio trial (bevacizumab or placebo plus radiotherapy/temozolomide for newly diagnosed glioblastoma) data, the MGMT status was not significantly different between patients with PsPD and PD." (PMID 32967367, 2020). "Studies often investigated the anatomic localization of glioblastoma with and without MGMT promoter methylation with visual examination, qualitatively, without a statistical, voxel-wise quantitative analysis." (PMID 32477929, 2020). "Two patients (2 HGGs) that were assessed for MGMT promoter methylation were found to be non-methylated; subjects 15 (Glioblastoma grade 4) and 23 (Anaplastic Astrocytoma grade 3)." (PMID 33373375, 2020). "Different expression levels of Olig2, Nogo-A, Nestin and AQP4 have no independent prognostic impact in IDH-wildtype glioblastoma and show no distribution differences regarding age, clinical status and MGMT-promoter methylation status." (PMID 32160197, 2020). "For glioblastoma multiforme, it has been shown that tumors with no or low levels of MGMT activity are more responsive to therapy with the alkylating drug temozolomide." (PMID 32841306, 2020). "In patients with MGMT unmethylated glioblastoma, no survival benefit was observed with ≥30% NCE resection (p = 0.884)." (PMID 32766140, 2020). "Similarly, hypomethylation of the MGMT promoter presumably resulting in increased MGMT expression, has been correlated with TMZ chemoresistance and worse survival in glioblastoma patients." (PMID 33318498, 2020).
glioblastoma (continued). "Cell toxicity was more pronounced in O6-methylguanine DNA methyltransferase (MGMT) promoter non-methylated glioblastoma cell." (PMID 30853913, 2019). "An increase in MGMT and MMP9 levels showed slightly poor prognoses of glioblastoma (p > 0.05)." (PMID 31653034, 2019). "However, mechanisms associated with adaptive resistance evolution of glioblastoma (GBM) relative to MGMT methylation remain unclear." (PMID 31575897, 2019). "A phase II trial, it compared radiochemotherapy with temozolomide to radiotherapy and temsirolimus in patients with newly diagnosed glioblastoma without MGMT promoter methylation." (PMID 31510109, 2019). "Methylated MGMT promoter particularly benefits the elderly glioblastoma patients in treatment with temozolomide than those none-methylated ones." (PMID 31708732, 2019). "We first tested whether glioblastoma TS cells, TS13-18 (with unmethylated MGMT gene promoter) and TS13-20 (with methylated MGMT gene promoter), were responsive to TMZ." (PMID 31658771, 2019). "In addition, temozolomide, a DNA alkylating agent, is only effective against tumors that have epigenetically silenced the DNA repair enzyme O6-methylguanine-DNA-methyltransferase (MGMT), which occurs in ~45% of all glioblastomas." (PMID 31632393, 2019). "Even though MGMT methylation does not offer as much predictive value for pituitary tumors as glioblastoma, finding clinically informative methylation markers remains the goal." (PMID 31139150, 2019). "And they also found that TMZ preferentially kills cancer stem cells in glioblastoma in MGMT-negative cell lines." (PMID 32010632, 2019). "MGMT (O6-methylguanine DNA methyltransferase) promoter methylation is inversely correlated with MGMT expression and patients’ response to the alkylating agent temozolomide with approximately 50% of grade IV glioma (usually glioblastoma, GBM) exhibiting MGMT promoter methylation." (PMID 31803237, 2019). "TMZ is less effective in glioblastomas lacking MGMT promoter methylation, resulting in worse outcome of this group of patients." (PMID 29854309, 2018). "In glioblastoma, DSF induced O6-methylguanine methyltransferase (MGMT) inhibition may increase response to alkylating chemotherapy." (PMID 30647912, 2018). "Both MGMT and STAT3 have been shown to mediate TMZ resistance in glioblastoma." (PMID 29949238, 2018). "Analysis of the TCGA glioblastoma dataset and the French glioma dataset gse16011, showed no variation in ARNT2 expression according to MGMT status, IDH1 mutation or EGFR amplification (not shown)." (PMID 29149419, 2018). "We focused on promoter methylation, because in glioblastoma this modification has been recognized as a predictive and prognostic factor for therapy with methylating agents, such as TMZ, and determination of MGMT promoter methylation status is standard practice for this tumor type." (PMID 30274152, 2018). "In particular, novel treatment options are highly needed for patients suffering from glioblastomas without MGMT promoter methylation who show limited benefit from TMZ chemotherapy." (PMID 29854309, 2018). "The mitotic inhibitor PTX represents a potential alternative chemotherapeutic agent for glioblastoma, as its potency does not depend on the cells’ MGMT status." (PMID 28976305, 2017). "Hence, increased patient-derived microvesicular MGMT and APNG mRNA levels are indicative of drug resistance or they predict alkylating drug responses in glioblastoma patients." (PMID 28730141, 2017). "For example, combining CIRT with temozolomide (TMZ) led to additive cytotoxicity in glioblastoma multiforme cell lines and the effect was independent of O6-methylguanine-DNA methyltransferase (MGMT)-expression." (PMID 28598362, 2017). "Deficiency in MSH6 has been found to cause resistance to TMZ and tumor progression irrespective of MGMT status in glioblastoma and in aggressive pituitary adenomas or carcinomas." (PMID 28900805, 2017).
glioblastoma (continued). "Also, the mRNA levels of microvesicular MGMT, APNG, or both were elevated in resistant glioblastoma cell lines as compared to sensitive cell lines." (PMID 28730141, 2017). "Although repeatedly reported as a good predictor, MGMT promoter methylation is not correlated with OST on both glioblastomas and LGG patients in our results." (PMID 28575062, 2017). "To date, there is no useful therapeutic alternative for alkylating agents in glioblastoma patients with high MGMT activity." (PMID 28976305, 2017). "The methylation status of the MGMT promoter has been observed in some cancers, such as non-small cell lung cancer, glioblastoma, and breast cancer." (PMID 27824946, 2016). "Moreover, a recent investigation (in which a molecular registry of 274 glioblastoma patients was used) showed that the poorest OS and PFS were observed in wild-type IDH1 glioblastomas with an unmethylated MGMT promoter." (PMID 27834917, 2016). "The randomized phase III CENTRIC and phase II CORE trials explored the integrin inhibitor cilengitide in patients with newly diagnosed glioblastoma with versus without O6-methylguanine DNA methyltransferase (MGMT) promoter methylation." (PMID 26918452, 2016). "In patients with newly-diagnosed glioblastoma, temozolomide (TMZ) is the standard of treatment; however, a challenge exists in overcoming TMZ drug resistance mainly due to O6-methylguanine DNA methyltransferase (MGMT)." (PMID 27898034, 2016). "We focused our investigation on miRNAs potentially intervening on MGMT RNA degradation, analyzing FFPE tissues from a cohort of 57 glioblastoma samples in which the MGMT promoter was non-methylated." (PMID 27057640, 2016). "Here we performed a genome-wide screening of 1,205 miRNAs in glioblastoma tissue samples with differential expression of MGMT mRNA in which MGMT gene promoter was non-methylated." (PMID 27057640, 2016). "MGMT promoter methylation and the published MGMT regulating microRNAs (miRNAs) do not completely explain the expression pattern of MGMT in clinical glioblastoma specimens." (PMID 27057640, 2016). "It has been suggested that MGMT expression may be regulated by inhibiting its upstream TF, such as SP1 in glioblastoma." (PMID 25514975, 2015). "In non-elderly glioblastoma patients, MGMT promoter methylation status does not fulfil the criteria of a predictive factor and does not directly guide therapeutic decisions, but it is a strong prognostic factor, which impacts clinical management." (PMID 26295302, 2015). "Similarly, a recent study showed that BMP2 can sensitize glioblastoma-stem-like cells to TMZ (500 μM) by downregulating both hypoxia-inducible factor-1α (HIF-1α) and MGMT." (PMID 26546412, 2015). "However, we found high steady state mRNA and MGMT protein expression levels not only in T98G, but also U251MG glioblastoma cells." (PMID 24678590, 2014). "Suppressing MGMT activity, therefore, could enhance the cytotoxicity of TMZ against melanoma and glioblastoma multiforme." (PMID 25295108, 2014). "Another report drew a similar conclusion, with no prognostic effect of MGMT promoter methylation being observed in tumors diagnosed in a central pathology review as glioblastoma." (PMID 25211033, 2014). "TMZ concentrations that are reached in patients were found to be only sufficient to completely eliminate glioblastoma stem cells in vitro from MGMT negative but not from MGMT positive tumors." (PMID 24678590, 2014).
glioblastoma (continued). "We examined 40 primary brain tumours (30 glioblastomas and 10 oligodendroglial tumours) with our new technique, namely double-labelling immunohistochemistry for MGMT and a "cocktail" of non-tumour antigens (CD34, CD45 and CD68)." (PMID 24252243, 2013). "A subpopulation of glioblastoma patients have low MGMT expression with no detectable promoter methylation, indicating that other molecular mechanisms also regulate MGMT expression." (PMID 24287492, 2013). "Both HeLa MR and U251 glioblastoma cells do not express MGMT and therefore exhibit zero colony survival at 0.2 μM MNNG (well within chemotherapeutic range), using the classic colony survival assay." (PMID 24019948, 2013). "The authors concluded that nimotuzumab shows a clear trend towards efficacy in MGMT non-methylated glioblastoma patients together with an excellent safety profile." (PMID 23782513, 2013). "Previous studies have demonstrated that the methylation of the MGMT promoter, which leads to the silencing of MGMT transcription, has a significant impact on the response to TMZ-based therapy and the survival in patients with newly diagnosed glioblastoma." (PMID 24265731, 2013). "However, despite these promising results, there are conflicting studies about the link between MGMT promoter methylation and TMZ sensitivity, suggesting that additional factors must be considered to predict glioblastoma sensitivity to TMZ." (PMID 22837675, 2012). "Glioblastoma patients with methylated MGMT were significantly younger than those whose tumor lacked methylation (P < 0.05) and an opposite was observed for CASP8 (P < 0.01)." (PMID 22672670, 2012). "The annotation of the MGMT status in the TCGA-GBM dataset according to MGMT-STP27 allowed determining that MGMT is not a CIMP gene in glioblastoma although CIMP tumors were more likely to be MGMT methylated." (PMID 22810491, 2012). "Based on these results, two randomized trials, CENTRIC and CORE, are currently ongoing to determine the efficacy of cilengitide for newly diagnosed glioblastoma with or without a methylated O6-methylguanine-DNA methyltransferase (MGMT) promoter." (PMID 21804824, 2012). "In contrast to glioblastoma, we found that MGMT methylation status was not important in TMZ response or survival of patients." (PMID 20736948, 2010). "Also epigenetic silencing of various genes has been described as overrepresented in either primary (NDRG2) or secondary (MGMT and EMP3) glioblastomas." (PMID 19333441, 2009). "In glioblastoma patients treated with radiotherapy alone, MGMT promoter methylation did not significantly influence survival, thus indicating that the MGMT promoter status is a predictive factor for response to chemotherapy." (PMID 19333441, 2009). "This was a randomized phase III clinical study evaluating the epigenetic inactivation of the MGMT gene as a predictive factor for benefit from adjuvant treatment with temozolomide plus radiotherapy compared with radiotherapy alone in patients with newly diagnosed glioblastoma multiforme (GBM)." (PMID 22275966, 2008). "Fluorescenceimaging confirmed efficient intracellular delivery of FAM-labeledsiRNA into T98G human glioblastoma (GBM) cells exclusively with G3-CYS,correlating with a marked reduction to 15–25% of control levelsin target protein expression of p42-MAPK, Rheb, and MGMT." (PMID 41334811, 2026). "Glioblastoma (GBM) is an incurable tumor where temozolomide (TMZ) resistance limits survival, even in MGMT-methylated patients." (PMID 41975220, 2026).